KDR (kinase insert domain receptor)
Diseases named in the same sentence as KDR in open-access papers (continued):
Sharing a sentence is not in itself a finding about the gene and the disease.
cancer (continued). "Notably, the co-gained regions included a small array of genes (human chromosome 4, zebrafish chromosome 20) that contains KDR, PDGFR and KIT; three genes identified as cancer drivers and potential drug targets in human MPNSTs." (PMID 24009526, 2013). "VEGF isoforms have different affinities for the VEGF receptors [VEGFR1 (flt1), VEGFR2 (KDR/flk1) and VEGFR3 (neuropilin)] and may play distinct roles in vascular development and diseases such as cancer growth and metastasis." (PMID 19922608, 2009). "The kinase insert domain-containing receptor (KDR; also known as vascular endothelial growth factor receptor 2: VEGFR-2) gene plays a critical role in cancer metastasis and is used as a molecular target in cancer therapy." (PMID 19435508, 2009). "Following stimulation with VEGF, KDR is translocated to the nucleus, demonstrating that VEGFR2/KDR is not a vasculature-restricted receptor but also has an additional role in cancer cell biology." (PMID 19435508, 2009). "VEGFR-2 (also known as KDR or FLK-1) is a high affinity tyrosine kinase receptor for VEGF, known to be very important in mediating normal and pathologic angiogenic responses, especially in cancer." (PMID 19517030, 2008). "The upregulation of KDR is consistent with the previously discussed role of VCP in regulating angiogenesis and vascular permeability and highlights its involvement in pathological conditions characterized by aberrant angiogenesis, such as in cancer and vascular diseases." (PMID 39802400, 2025). "In addition, DHX9 expression in most cancer types had an obvious positive correlation with several checkpoints, such as TGFBR1 (transforming growth factor-beta receptor 1), KDR (vascular endothelial growth factor receptor-2, VEGFR-2), and CD274 (PD-L1)." (PMID 37214432, 2023). "In addition, VEGFA and B, their receptors KDR and FLT1, and downstream TFs, including KLF4 and ETS1, were found in this analysis as targets of cooperative ENHs, in line with the pivotal role of angiogenesis in promoting cancer metastatic spreading." (PMID 37408506, 2023). "In LUAD, we found a prominent upregulation of the KDR-VEGFA axis from cancer cells toward neutrophils, macrophages/monocytes, mast cells, and classical dendritic cells (cDCs), potentially implicating immunosuppressive signaling by cancer cells in this histotype." (PMID 36368318, 2022). "Vascular endothelial growth factor (VEGF) and its receptor vascular endothelial growth factor receptor (VEGFR)-2 or kinase insert domain receptor (KDR) are key regulators of angiogenesis, which plays a key role in the growth of solid tumors and contributes to the progression of cancer metastasis." (PMID 27752293, 2016). "B-RafV600E synergistically works with vascular endothelial growth factor receptor 2 (KDR) to promote the occurrence and progression of cancers, and the development of dual-target drugs simultaneously against these two kinds of kinase may offer a better treatment advantage." (PMID 26501259, 2015). "For diverse immune inhibitors, KDR and CD274 demonstrated the most significant negative relationship with METTL1 among nearly all cancers." (PMID 35432338, 2022). "Two additional genes known primarily for their contribution to angiogenesis, VEGFR2 (KDR) and Ephrin A2 (EPHA2), were lowly expressed by the human cancer cells and did not change in response to aspirin treatment." (PMID 32246008, 2020). "Additionally, many of these markers, namely, KDR, FLT4, and UNC5A, have been shown to be involved in other types of cancers, making these markers non-exclusive to KS tumorigenesis." (PMID 37046832, 2023).
infection (39 papers, 2009 to 2025). The state of being infected such as from the introduction of a foreign agent such as serum, vaccine, antigenic substance or organism. "The top upregulated genes in KSHV lytic and mixed infection spots are predicted to encode proteins that regulate angiogenesis including ADAMTS9, KDR and PGF, endothelial cell development including KDR and STC1, and cell-substrate adhesion, SPRY4, ITGA1, ADAMTS9, KDR, MMP12." (PMID 39386738, 2024). "Upon high VL infection, a set of core responsive DEG found in the transporters and VEGF signaling gene groupings (KDR, HPSE, and SLC16A10) were significantly (P < 0.05) downregulated in the fetal placenta." (PMID 40119254, 2025). "To further characterize the phenotype of myeloid cells with elevated expression of VEGFR2, we utilized a CD11b+Gr-1+ MDSC-like cell line, J774M, and expressed human VEGFR2, KDR, by lentiviral infection." (PMID 34673569, 2021).
cardiovascular diseases (27 papers, 2010 to 2025). "Kinase insert domain receptor (KDR) gene is responsible for the transcription of vascular endothelial growth factor receptor 2 (VEGFR2) that plays a major role in the cardiovascular diseases (CVDs) and platelet aggregation." (PMID 33665428, 2021). "CD34+KDR+ CACs are markers of vascular injury although the mechanisms for their increases or decreases in the circulation of patients with cardiovascular diseases are unclear." (PMID 28278173, 2017). "Stratification with respect to the expression of CD45 indicates that specifically the CD45dimCD34+KDR+ cell population correlates with cardiovascular disease and is significantly regulated by statin treatment, suggesting that the CD45dim fraction contains the prognostic relevant EPC populations." (PMID 21072182, 2010). "Moreover, we also examined whether the KDR gene SNPs and serum KDR levels are related to the development of cardiovascular disease (CVD) in our RA patients." (PMID 31405022, 2019). "The HIF-1 signaling pathway is closely related to hypoxia–ischemia in cardiovascular diseases, and we found four genes (FLT1, KDR, ANGPT2, and PGF) related to angiogenesis in the pathway." (PMID 36435742, 2022). "In patients with cardiovascular disease, numbers of circulating CD34+KDR+ EPC are inversely related to vascular damage." (PMID 23936333, 2013). "In the cardiovascular system, VEGFR-2 (also known as KDR, flk-1) is mainly expressed in endothelial cells, which is crucial to the maintenance of cardiovascular physiological function and the development of pathological processes of cardiovascular diseases." (PMID 35604528, 2022). "Through the interaction with endothelial cell membranes and FLT1, KDR or NRP1 receptors and the subsequent activation of RAS and MAPK kinases signalling cascades, VEGF is a powerful inducer of angiogenesis, which can have a very important role in cardiovascular diseases." (PMID 35736920, 2022).
retinopathy (26 papers, 2012 to 2023). "Elevated miR-223-3p showed increased expression of angiogenic markers, VEGF, FLT-1 and KDR compared to controls at 2% glucose, confirming its role in zebrafish retinopathy in the developmental stage." (PMID 36869348, 2023).
adenocarcinoma (21 papers, 2009 to 2025). A common cancer characterized by the presence of malignant glandular cells. "Interestingly, KDR is also expressed in the malignant compartment in adenocarcinoma at threefold higher levels than in SCC (p = 1 × 10− 5, t-test)." (PMID 32381040, 2020). "Additionally, GREM1 has been shown to bind and activate the vascular endothelial growth factor (VEGF) receptor Kinase Insert Domain Receptor (KDR, also known as VEGFR2, one of two receptors for VEGF), which is expressed in endothelial cells of both adenocarcinoma and SCC." (PMID 32381040, 2020). "To test if GREM1 may have an autocrine function in these cells, we knocked down the transcript in high GREM1 expressing H1755 (which does not express the KDR receptor) and H1792 (which does express KDR) adenocarcinoma cells using siRNA." (PMID 32381040, 2020).
neurodegenerative disease (7 papers, 2016 to 2025). A disorder of the central nervous system characterized by gradual and progressive loss of neural tissue and neurologic function. "KDR, also known as vascular endothelial growth factor receptor 2 (VEGFR-2), is linked to various neurodegenerative diseases, including Alzheimer’s, and affects microglial function and neuroinflammation processes, particularly through the regulation of downstream signaling pathways like PI3K/Akt." (PMID 39201475, 2024).
KDR also shares sentences with these, for which no sentence is quoted: liver cancer (53 papers); liver fibrosis (26); clear cell renal cell carcinoma (25); metastatic colorectal cancer (24); acute myeloid leukemia (22); fibrosarcoma (22); kidney cancer (22); pulmonary fibrosis (22); gastrointestinal stromal tumor (21); cholangiocarcinoma (19); ovarian tumor (19); COVID-19 (16); heart failure (16); metastatic carcinoma (16); Sepsis (16); Hand-foot syndrome (15); multiple myeloma (15); prostate tumor (15); renal fibrosis (15); age-related macular degeneration (14); colitis (14); hypothyroidism (14); metastatic melanoma (14); pancreatic neuroendocrine tumor (14); psoriasis (14); diabetic nephropathy (13); idiopathic pulmonary fibrosis (12); Thrombocytopenia (12); Alzheimer disease (11); gastric tumor (11).
A further 511 diseases each share a sentence with KDR in 11 papers or fewer.